IDH2 (isocitrate dehydrogenase (NADP(+)) 2)
Diseases named in the same sentence as IDH2 in open-access papers (continued):
Sharing a sentence is not in itself a finding about the gene and the disease.
tumor (continued). "However, metastases or recurrent disease appeared to occur less frequently in patients with IDH2 G2/3 tumours compared to IDH1 and IDHwt tumours (% metastases/recurrence, IDH1: 37%, IDH2: 13%, IDHwt: 23%, IDH1 vs IDH2: p = 0.04)." (PMID 36042521, 2022). "Additionally, we performed a differential protein expression analysis comparing the ACC, NEC-like IDH2 and NEC-like SMARCA4/ARID1A tumor classes against each other." (PMID 36443295, 2022). "The age at diagnosis for each IDH group was similar for ACT/G1 and DD CS, and the difference in age of the G2/3 tumours explained the overall difference in ages (median age G2/3, IDH1: 60 year, IDH2: 71 year, IDHwt: 44 year, IDH1vs IDH2: p = 0.04, IDH1 vs IDHwt: p = 2e−6)." (PMID 36042521, 2022). "Consistent with in vitro results, cells without IDH2 showed slower primary tumor growth and increased number, but not size, of liver metastatic foci." (PMID 35356277, 2022). "Genes and proteins regulating the TCA cycle (PDHA1, SUCLG2, SUCLG1, and IDH2) as well as mitochondrial function (VDAC1, MRPS31, LARS2, OPA1, and MTIF2) showed higher transcripts and protein levels in Wnt‐high compared with Wnt‐low tumor entities." (PMID 35904277, 2022). "These tumours are characterised by the presence and absence of IDH1 and IDH2 mutations, and recently, TERT promoter alterations have been reported in around 20% of cases." (PMID 36042521, 2022). "This association was observed in G2/3 (IDH1 vs IDH2: p = 7e−6) but not in DD CS (IDH1 vs IDH2: p > 0.99), implying that although TERT is associated with high-grade tumours, this is not equal in the context of IDH mutation status." (PMID 36042521, 2022). "The 20–30% of central cartilaginous tumours without an IDH1/2 mutation highlights the need for additional prognostic biomarkers for patients whose tumours are WT for IDH1, IDH2 and GNAS mutations." (PMID 34528398, 2021). "In hypoxic tumor cells, IDH1 and IDH2 mediate the reversal of the TCA cycle." (PMID 33727360, 2021). "Clinical trials have begun after preclinical studies demonstrated the efficacy of small molecule inhibitors against mutant forms of IDH1 and IDH2 accompanied by a reduction of (R)-2-HG levels, which resulted in a block of de-differentiation and growth suppression of AML tumor cells." (PMID 31105869, 2019). "Although IDH2-R140Q increased tumor colony formation, this effect was found not to be statistically significant." (PMID 31105869, 2019). "Given the importance of IDH2 in the biogenesis of tumor cells and our findings including unchanged expression of IDH1, we speculate that IDH2 plays a crucial role in metabolic reprogramming and biological processes related to GH-PA." (PMID 31455412, 2019). "Perhaps most fascinating is our observation that ‘oncometabolite’ (R)-2-HG is not mitogenic for tumor cells that carry normal IDH2." (PMID 31105869, 2019). "IDH2 was more abundant in WT MEFs than in KO and is responsible for the production of NADPH, whereas NADPH is essential for the proliferation of both normal and tumor cells." (PMID 30166528, 2018). "In other words; in this era of high throughput sequencing, finding IDH2 R172, for instance, in a tumor does not necessary mean that it is and early nor a driver one." (PMID 28785398, 2017). "All samples were primary tumours, fresh frozen and IDH1 and IDH2 wild type." (PMID 27886174, 2016). "Intriguingly, one tumour was co-mutated for IDH1 (R132H) and IDH2 (P162S), but exhibited no distinguishing phenotype in terms of clinicopathology or mutation rate." (PMID 26068201, 2015). "PC, ACO1, IDH2 and PCK1 and were overexpressed in tumor samples from liver metastases only." (PMID 22412968, 2012). "However, in tumor cells, reductive carboxylation of AKG may occur through IDH2 or its cytosolic isoform IDH1." (PMID 40863152, 2025).
tumor (continued). "Notably, G6PD and IDH2—key enzymes in the pentose phosphate pathway and TCA cycle respectively—may protect tumor cells from radiation-induced oxidative damage through enhanced NADPH production and antioxidant capacity." (PMID 41306526, 2025). "Additionally, GNAQ, GNAS, JAK2, NRAS, IDH2, and CTNNB1 are cancer-related genes that may be related to tumor metastasis." (PMID 36780540, 2023). "NEC-like IDH2 and NEC-like SMARCA4/ARID1A tumors also demonstrated strong overexpression of proteins specific for neurons or cells of the diffuse neuroendocrine system such as UCHL1, CRMP1 and ENO2, strongly indicating a neuroendocrine differentiation for both tumor classes." (PMID 36443295, 2022). "In this group of patients, mutations in IDH2 (n = 3), KRAS (n =3), KIT (n = 3), and SETD2 (n = 1) were identified at low AF (median, 0.86%; range, 0.68 to 2.9%), though the corresponding mutation in the primary tumor was not known." (PMID 35273917, 2022). "In addition, although not statistically significant, stage IV tumor samples showed higher IDH2 levels compared to stage III tumors." (PMID 35205159, 2022). "Quantification of immunohistochemical staining of both tumor cells and the tumor microenvironment showed a slight tendency towards higher levels (as opposed to lower levels in the proteomic analysis) of IDH2 protein expression in MPN-AITL samples compared with R-AITL samples (p = 0.105)." (PMID 34771688, 2021). "However, none of the mutations are exclusively observed in one tumour type, suggesting a similar effect of all IDH1 and IDH2 mutations on tumourigenesis." (PMID 31728625, 2020). "Indeed, mouse models treated with IDH2 inhibitors had decreased R-2-HG production, of the tumor growth, but not their differentiation." (PMID 30708988, 2019). "Among the proteins of interest (NPM1, FLT3, DNMT3A, IDH1, IDH2, KIT, and RAS), non-mutation bearing ligands from NPM1 were the most frequent in both patient tumor samples and cell lines, including ligands close to or corresponding to where hotspot mutations occur (EAIQDLWQW and MTDQEAIQDLWQWR)." (PMID 31291378, 2019). "The dying part of tumor tissues may also release IDH1 and IDH2 protein or spread into blood, which may contribute to increasing of serum IDH2 level and a part of the IDH1 and IDH2 detected." (PMID 29465809, 2018). "Tumor DNA was analyzed for alterations in selected genetic loci (1p36, 9p22, 10q23–24, 17p13, 19q13, 22q12), isocitrate dehydrogenase 1 (IDH1), isocitrate dehydrogenase 2 (IDH2) and the CpG island methylation status of critical tumor-related genes (MGMT, P16, DAPK, PTEN, RASSF1A, Rb1)." (PMID 23826216, 2013). "Furthermore, IDH2 is required for tumor maintenance rather than simply for tumor initiation." (PMID 25502799, 2014). "IDH2 had a negative correlation with miR‐758‐3p and a positive correlation with circ_0028826 in NSCLC tumor tissues by Pearson's correlation analysis." (PMID 39113352, 2024). "Immunohistochemical evaluation of IDH2, DNAJA2 and citrate synthase showed diffuse cytoplasmatic staining of both neoplastic and non-neoplastic cells in the tumor microenvironment in both MPN-AITL and R-AITL samples." (PMID 34771688, 2021). "In multivariate Cox regression analysis, high IDH2 protein expression was an independent predictor of shorter BCSS (HR 1.4; 95% CI 1.1–1.9; p = 0.042) regardless of the tumour grade, lymph node stage and nodal status." (PMID 31599393, 2020). "Expression levels of IDH2 were higher in HCC samples compared to adjacent non-tumor samples (P = 0.0010) from the GSE36376 data set, while IDH2 expression showed no changes in the TGA-LIHC data set (P = 0.7106)." (PMID 30430110, 2018). "Although we were not able to include tumors from this class in our proteomics study due to insufficient quantities of tumor tissue, we did not detect immunohistochemical expression of the neuroendocrine and neuronal markers that were upregulated in NEC-like IDH2 and NEC-like SMARCA4/ARID1A tumors." (PMID 36443295, 2022).
tumor (continued). "Second, nonattendance of the tumor-related variables, such as MGMT methylation status and isocitrate dehydrogenase-1 (IDH-1) and IDH-2, and local/systemic reactive proinflammatory cytokine/chemokine levels disallowed us to perform SII group-based analysis according to these biomarkers." (PMID 32565725, 2020). "Similarly, in the second patient, inference of clones from the bulk sequencing data failed to predict the presence of the IDH2 (R140Q), NRAS (G13R) double-mutant clone comprising ∼30% of the total tumor population." (PMID 30087104, 2018). "Notably, the IDH2 (R140Q) NRAS (G13R) clone was not predicted from the bulk sequencing VAFs, yet it represented 29% of the diagnosis tumor defined by single-cell DNA sequencing." (PMID 30087104, 2018).
cancer (326 papers, 2011 to 2026). A tumor composed of atypical neoplastic, often pleomorphic cells that invade other tissues. "Mutated IDH1/IDH2 enzymes represent a prime example of the intersection between metabolic and epigenetic dysregulation in cancer biology." (PMID 40181550, 2026). "Alterations in DNA methylation caused by mutations in IDH1 and IDH2 are common in a wide range of cancers." (PMID 40641934, 2025). "Further exploration of the effects of individual IDH1/2 mutations on DNA methylation is arguably warranted, given that the frequencies of specific IDH1 and IDH2 driver mutations vary across other cancer types." (PMID 40545636, 2025). "Mutations in isocitrate dehydrogenase 1 (IDH1) and IDH2 not only rewire cellular metabolic pathways but also reshape epigenetic landscapes to promote tumorigenesis, acting as key drivers in various cancers." (PMID 41335282, 2025). "Cancer cells with IDH1 or IDH2 mutations cause accumulation of 2-HG, which supports the cancer cells by maintaining a stem-like phenotype, while suppressing T-cell- and macrophage-mediated immune activity." (PMID 41235226, 2025). "The abnormal accumulation of the metabolite D-2-HG in cancers is mainly due to IDH1/IDH2 mutations, which leads to the over-production of D-2-HG." (PMID 41236698, 2025). "Driver mutations in IDH1 and IDH2 have been implicated in several cancer types, including central chondrosarcoma, acute myeloid leukemia, and glioblastoma." (PMID 41299743, 2025). "Although IDH2 mutations are well-known oncogenic events in several cancer types, the role of wild-type IDH2 in cancer remains elusive." (PMID 38658533, 2024). "We observed increased NO2− production in IDH2-deficient macrophages co-cultured with cancer cells (LLC1)." (PMID 39256649, 2024). "IDH1 and IDH2 mutations drive cancer through excessive D-2-hydroxyglutarate (D-2HG) production, disrupting metabolism and epigenetic regulation, and serve as biomarkers for detection and targeted therapy in specific cancers." (PMID 39767571, 2024). "IDH2-deficient macrophages co-cultured with cancer cells were found to possess increased mitochondrial dysfunction and fission than wild-type BMDM." (PMID 39256649, 2024). "We found that Ki67 expression was significantly reduced in cancer cells co-cultured with IDH2-deficient macrophages." (PMID 39256649, 2024). "Future research should focus on refining IDH2 inhibitors, exploring their use in various cancer types, and fully elucidating the mechanisms underlying IDH2’s role in both oncogenesis and immune cell function." (PMID 39409901, 2024). "Isocitrate dehydrogenase (IDH) 1 and 2 (IDH1 and IDH2) are the most frequently mutated metabolic genes in human cancers." (PMID 38581001, 2024). "Although the impact of IDH2 mutation on cancer development through the generation of oncometabolite 2-hydroxyglutarate has been well-characterized, the role of wild-type IDH2 in cancer remains to be further defined." (PMID 38658533, 2024). "Recent studies have suggested that wild-type IDH2 promotes cancer growth, whereas IDH2 deficiency suppresses tumorigenesis." (PMID 39256649, 2024). "These discoveries have led to the development of specific IDH1/2-mutant inhibitors, such as ivosidenib and enasidenib, which are successful examples of targeting cancer metabolism in patients with IDH1- or IDH2-mutated acute myeloid leukemia." (PMID 39409901, 2024). "The reference is based on a single IDH2 variant that is depleted in the cells that we identify as cancer." (PMID 39163479, 2024). "IDH1 and IDH2 are frequently mutated in various types of cancer, including glioma, acute myeloid leukemia, cartilaginous tumors, etc.." (PMID 38167476, 2024). "In cancer cells (LLC1) co-cultured with IDH2-deficient macrophages exhibiting the M1 phenotype, the levels of metastasis-related EMT marker fibronectin were decreased, whereas those of E-cadherin were increased." (PMID 39256649, 2024).
cancer (continued). "The mobility and migratory ability of cancer cells (LLC1) were suppressed when they were co-cultured with IDH2-deficient macrophages." (PMID 39256649, 2024). "Expectedly, the levels of M2 macrophage-related markers Arg1, p-AMPK, and p-STAT3 showed a tendency to decrease in IDH2-deficient macrophages co-cultured with cancer cells." (PMID 39256649, 2024). "The proliferation and migration of cancer cells were significantly diminished by IDH2 deficiency in macrophages." (PMID 39256649, 2024). "IDH1 and IDH2 are frequently mutated in cancer, which alters their activity so instead of generating NADPH, NADPH is consumed by the reduction of α-KG to generate 2-HG." (PMID 38674143, 2024). "As hypermethylation and upregulation of the repressive H3K27 epigenetic mark are hallmarks of IDH2-mutated carcinomas, DNA methylation-based classification is conceivable." (PMID 38315310, 2024). "The spectrum is expanding, with IDH2 mutations documented in poorly differentiated high-grade carcinomas occurring in the sinonasal/paranasal anatomical boundaries as well as a handful of high-grade olfactory neuroblastomas." (PMID 38315310, 2024). "Isocitrate dehydrogenase (IDH1 and IDH2) mutations are evident in many types of cancers including glioblastoma, and acute myeloid blood (AML)." (PMID 37580393, 2023). "These alterations, including oncogenic mutations in PIK3CA and IDH2, have already been categorized as Level 1 alterations in other cancer types, but are still emerging as potential therapeutic targets in NSCLC." (PMID 38155717, 2023). "IDH1 and IDH2 are the most frequently mutated metabolic genes in human cancer, and their mutations have been identified in different types of cancer, notably in gliomas, secondary glioblastomas, cartilaginous and bone tumors, and acute myeloid leukemia." (PMID 37601653, 2023). "IDH2 is the most commonly mutated metabolic gene in cancer, and it disrupts metabolic and epigenetic regulation, promoting tumorigenesis in humans." (PMID 35880695, 2023). "Here, we used synthetic C3- and C4-alkylated 2OG derivatives to investigate the substrate selectivities of the most common cancer-associated IDH1 variant (R132H IDH1), of two cancer-associated IDH2 variants (R172K IDH2, R140Q IDH2), and of WT IDH1/2." (PMID 36621625, 2023). "The increase of (R)-2HG in cancers with IDH1 or IDH2 mutations and metabolic preferences that distinguish cancers with unique oncogenotypes are examples of divergent pathways." (PMID 36597205, 2023). "Virtually almost all IDH1 and IDH2 mutations are missense mutations located at R132 and R172, respectively; both isotypes are therefore promising biomarkers for cancer diagnosis and gene therapy." (PMID 36959802, 2023). "IDH is one of the most studied genes in glioma development, and cancers with IDH1 or IDH2 mutations produce 10–100 times more 2-HG than those with the IDH1 or IDH2 wildtype." (PMID 36819921, 2023). "Conversely, downregulation of IDH2, as observed in certain types of cancer, is associated with decreased levels of 5-hmC." (PMID 35269796, 2022). "Both IDH1 and IDH2 mutations have been reported in cancers, whereas usually only one mutation is identified in a certain cancer." (PMID 35814406, 2022). "Point mutations in the isocitrate dehydrogenases IDH1 and IDH2 have been confirmed as oncogenic drivers in only 0.9%–3% of all cancers." (PMID 35732120, 2022). "Isocitrate dehydrogenase (IDH) enzymes IDH1 and IDH2 are frequently mutated in several cancers and a gain-of-function activity promotes conversion of α-ketoglutarate (α-KG) to the oncometabolite 2-Hydroxyglutarate (2-HG)." (PMID 36048239, 2022). "On the other hand, mutations in IDH2 have been observed in various human cancers, including CRC; these mutations have been associated with a loss of IDH2 native enzymatic activity." (PMID 35205159, 2022). "Mutated IDH2 promotes cancer progression through metabolic reprogramming and epigenetic deregulation of gene expression." (PMID 36335201, 2022).